USP15 (ubiquitin specific peptidase 15)
Diseases named in the same sentence as USP15 in open-access papers (continued):
Sharing a sentence is not in itself a finding about the gene and the disease.
viral meningitis (1 paper, 2024). Inflammation of the membranes surrounding the brain and spinal cord due to a viral infection. "We speculated that the lncRNA AC002511.1 may act as a ceRNA to capture hsa-miR-199b-5p to regulate the expression of ANKRD22 and USP15 in the viral meningitis group." (PMID 38347610, 2024). "In viral meningitis subjects, the ceRNA network was composed of hsa-miR-199b-5p, 4 mRNAs (ANKRD22, EVI2A, USP15, and C8orf88), and AC002511.1." (PMID 38347610, 2024). "CeRNA networks showed that ANKRD22 and USP15 were targets of hsa-miR-199b-5p and lncRNA AC002511.1 were co-expression with hisa-miR-199b-5p in viral meningitis patients." (PMID 38347610, 2024).
vitiligo (1 paper, 2025). Generalized well circumscribed patches of leukoderma that are generally distributed over symmetric body locations and is due to autoimmune destruction of melanocytes. "The overexpression of USP15 has been previously reported in vitiligo skin tissues as well as in the blood of patients with vitiligo." (PMID 40277891, 2025).
cancer (56 papers, 2015 to 2025). A tumor composed of atypical neoplastic, often pleomorphic cells that invade other tissues. "Recent study also indicated that USP15 is a key DUB causing IMiD resistance since USP15-overexpressed cancer cells are often insensitive to IMiD-induced protein degradation." (PMID 38582446, 2024). "Within our cohort, a high level of USP15 expression was associated with significantly decreased risk for mortality and cancer relapse." (PMID 36900163, 2023). "High expression of USP15 was associated with significantly decreased risk for cancer relapse: hazard ratio 0.420, p = 0.0089 (log-rank test)." (PMID 36900163, 2023). "In HCC patients, high expression of USP15 in tumor tissue was associated with significantly decreased risk for mortality and cancer relapse." (PMID 36900163, 2023). "For instance, another cancer-associated DUB, USP15, deubiquitylates transforming growth factor-β type I receptor (TGFβRI) and thus augments Smad-mediated signaling during cancer cell metastasis, while also attenuating insulin-like growth factor signaling." (PMID 36825571, 2023). "Alterations of USP enzymes are implicated in the pathogenesis of various cancers and USP15 has been reported to be overexpressed in MM cells and inhibit MM apoptosis." (PMID 35544413, 2022). "The deubiquitinating enzyme USP15 is implicated in several human cancers by regulating different cellular processes, including splicing regulation." (PMID 35027535, 2022). "Here, we have discussed the signaling networks regulated by USP15 that are predominantly involved in various cellular pathways associated with cancer and other related diseases." (PMID 33946990, 2021). "Inappropriate regulation of USP15 modification is associated with certain types of cancer and several other diseases." (PMID 33946990, 2021). "Many of the proposed substrates of USP15 in different cancer-associated pathways are involved in several signaling cascades." (PMID 33946990, 2021). "It has also been reported that USP15 is a crucial regulator which is associated with cancer-relevant pathways." (PMID 33771975, 2021). "Of note, high expression of USP15 is statistically associated with tissue-independent poor survival within the pan-cancer (PANCAN) patient cohort, a feature generally associated with oncogenes." (PMID 33378683, 2020). "Ubiquitin-specific protease 15 (USP15) is a widely expressed deubiquitylase that has been implicated in diverse cellular processes in cancer." (PMID 29429988, 2018). "One DUB that has recently received a lot of attention, primarily through its well-documented association with various cancer-signaling pathways, is the ubiquitin-specific peptidase 15 (USP15)." (PMID 28074857, 2017). "Here, we review how the USP15 domains function in deubiquitination of protein substrates, and comprehensively describe the connection between USP15 and signaling pathways associated with cancer and other diseases." (PMID 28245560, 2017). "Here, using in vivo CRISPR screens, the authors integrate human cancer genomics and mouse models, identifying that loss of USP15 or SCAF1 accelerates tumor development and leads to reduced inflammatory responses and increased sensitivity to PARP inhibition and Gemcitabine." (PMID 38902237, 2024). "Cancer‐associated USP15 mutations increase PARP inhibitor sensitivity in cancer cells." (PMID 37888853, 2023). "Thus, this study explores the molecular and cellular mechanism by which USP15 is implicated in cancer progression through the regulation of the TRAF6-BECN1 signaling axis for autophagy induction." (PMID 35422093, 2022).
cancer (continued). "As aberrant alternative splicing is a critical cause of cancer development, we sought to find the genes regulated by USP15 and USP4, which may, in turn, affect the cancer progression phenotype." (PMID 35027535, 2022). "Finally, we investigated the potential role of USP15 as a restriction factor for HPV E6-linked cancer cell survival." (PMID 31749782, 2019). "We brought new insights for the cancer patients with USP15 mutations." (PMID 30874560, 2019). "Hence, this review will provide a comprehensive overview of the regulatory mechanisms of USP15, particularly in different cancer-associated signaling pathways, which might raise its potentiality as a target for cancer therapy and other clinical applications." (PMID 33946990, 2021). "Their work demonstrated that USP15 knockout enhanced cancer cell migration and invasion and that USP15 attenuated autophagy through BECN1 deubiquitination." (PMID 40762380, 2025). "Subsequently, we performed qRT-PCR, WB, and immunohistochemistry analyses of the specimens from the 52 patients with HCC finding that USP15 expression levels in cancer tissues were significantly higher than those in adjacent tissues." (PMID 39794359, 2025). "Numerous lines of evidence implicate USP15 as a key driver of tumor progression across multiple cancers." (PMID 40762380, 2025). "Across all six probes—targeting ACE2, CATB, METAP1/2, MMP14, plasmin, and USP15—significantly elevated protease activity was observed in cancer patients compared to healthy controls." (PMID 40890441, 2025). "In various cancers, USP15 has been validated to exhibit up-regulated expression, impacting the initiation and progression of cancer." (PMID 38656882, 2024). "The Cancer Genome Atlas (TCGA) database showed that USP15 was amplified in many types of tumors, including GC." (PMID 39164728, 2024). "Analysis of a pan-cancer project showed that USP15 was amplified in about 4% of different type of cancers, including GC." (PMID 39164728, 2024). "Given the wide range of USP15 substrates and USP15-regulated pathways with well-known functions in cancer, we set out to elucidate USP15’s exact role in PDAC suppression." (PMID 38902237, 2024). "The current finding provides more evidence about the USP15 oncogenic function, especially during BRAFV600E mutated cancers." (PMID 38750011, 2024). "The mRNA level of USP15 in most GC cell lines was upregulated based on the Cancer Cell Line Encyclopedia (CCLE) database." (PMID 39164728, 2024). "USP15 is overexpressed in immunomodulatory drug (IMiD)-resistant cells, and targeting USP15 sensitizes these cells to IMiD, indicating that ubiquitination is important in cancer." (PMID 37176148, 2023). "Some authors have reported that the increased expression of USP15 is related to the development of several types of cancers." (PMID 37373211, 2023). "One important gene involved in cellular deubiquitination mechanisms is USP15, which is involved in critical cellular and oncogenic processes, and its expression is deregulated in several types of cancers." (PMID 37373211, 2023). "USP15 has been reported to promote or inhibit tumorigenesis and its progression in different cancers." (PMID 35203682, 2022). "Utilizing publicly available data from The Cancer Genome Atlas, we first evaluated USP15 mRNA expression across all reported tumor types." (PMID 34465865, 2022). "The following sections will review, in detail, the important functions of USP15 in cancers and other diseases." (PMID 35203682, 2022). "This review combines recent USP15-related research to illustrate the multi-faceted role of USP15 in cancer and other diseases." (PMID 35203682, 2022). "Here, we will provide a comprehensive overview of the role of USP15 in various cancers and other diseases, which will help us better understand the biological functions of USP15 and provide strategies for USP15 as a therapeutic target." (PMID 35203682, 2022).
cancer (continued). "Our analyses indicate that USP15 expression in AML exceeds that of other cancer types and that AML patient samples and cell lines express significantly higher levels of USP15 as compared to normal hematopoietic cells." (PMID 34465865, 2022). "USP15 has previously been reported to be a key factor in tumor pathogenesis and a potential therapeutic target of cancers." (PMID 35013132, 2022). "Several previous basic studies have revealed the versatile roles of USP4, USP11, and USP15 in different physiological and pathological processes, particularly in cancers." (PMID 33946990, 2021). "An opposite role is mediated by the deubiquitinase USP15 (Ubiquitin Specific Protease 15), which is overexpressed in several cancers, including ovarian carcinoma." (PMID 34298679, 2021). "USP15 is previously reported to be dysregulated in many human cancers and plays critical roles in tumor development and progression." (PMID 31952546, 2020). "The deubiquitinating enzyme ubiquitin-specific peptidase 15 (USP15) regulates diverse cellular processes in cancer." (PMID 31952546, 2020). "More interestingly, patients carried USP15 mutations that disrupted USP15-BARD1 interaction, and the cancer cell is more sensitive to PARP inhibitor." (PMID 30874560, 2019). "Here, we report that the deubiquitylating enzyme USP15 affects cancer cell response to PARPi by regulating HR." (PMID 30874560, 2019). "In this study, we found that the deubiquitinase USP15 plays an important role in HR and cancer cells’ response to PARP inhibitors." (PMID 30874560, 2019). "We found that knockout (KO) of USP15 by CRISPR sensitized cancer cells to DNA-damaging agents, including camptothecin (CPT), mitomycin C (MMC), hydroxyurea (HU), and ionizing radiation (IR)." (PMID 30874560, 2019). "Overall, consistent research and progress of current studies will lead to a stronger understanding and a more comprehensive view of USP15 functions in cancer and their role in future treatment strategies." (PMID 30874560, 2019). "As USP15 has multiple verified and candidate substrates, it is difficult to assess the relative importance for regulation of TOP2A in USP15 amplified and/or USP15 isoform-1 overexpressing cancer cells." (PMID 29429988, 2018). "USP15 has been shown to stabilize transcription factors, to be amplified in many cancers and to mediate cancer cell survival." (PMID 30459344, 2018). "Further investigation showed that USP15 interacts with another molecule known to be involved in development of many cancers." (PMID 30459344, 2018). "USP15 is emerging as a multifunctional DUB regulating also multiple proteins involved in cancer relevant pathways thereby mediating both, tumor suppressing and oncogenic functions in a context dependent manner." (PMID 29299163, 2017). "Abnormal expression of USP15 has been identified in various cancers and other diseases." (PMID 39151099, 2025). "The role of USP15 in cancer progression has been a subject of increasing interest in recent years." (PMID 40762380, 2025). "Given that several members of the USP family have been shown to promote cancer metastasis when dysregulated, we investigated whether USP15 contributes to NSCLC cell invasiveness." (PMID 40762380, 2025). "Through high-throughput sequencing, we found that the USP15 expression was higher in cancer tissue than that in paired adjacent tissues, suggesting that USP15 may affect HCC malignant progression." (PMID 39794359, 2025). "Moreover, USP15 is upregulated in many cancers and increases the stability of oncoproteins through deubiquitination modification, thereby promoting cancer progression." (PMID 39794359, 2025). "Moreover, the involvement of USP15 in the mechanisms of DNA repair has also been shown across various cancer types." (PMID 40762380, 2025).
cancer (continued). "Probe designed to be cleaved by cathepsin B showed the strongest discrimination between cancer and control samples, while probes designed to be cleaved by ubiquitin-specific peptidase 15 and plasmin were identified as the most informative subtype-specific markers for UGIC and CRC, respectively." (PMID 40890441, 2025). "Thus, focusing on USP15 offers a significant therapeutic potential to improve the efficacy of CRBN-based PROTAC treatments for the treatment of cancer." (PMID 39048965, 2024). "Moreover, upregulation of USP15 was found to drive cancer progression through the activation of the NF-κB signaling pathway." (PMID 38656882, 2024). "Notably, poly (ADP-ribose) polymerase inhibitors (PARPis) are DNA-damaging agents developed for cancer therapy, and USP15 has been shown to affect the response of cancer cells to PARPis by regulating HRR." (PMID 39522000, 2024). "However, the dual function of USP15 in regulating the progression of different cancers has been determined." (PMID 39522000, 2024). "The correlation of high survival rate and reduced cancer relapse with high expression of USP15 might suggest a role of USP15 as a tumor suppressor." (PMID 36900163, 2023). "While defects in RNA splicing are involved in various diseases including cancer, it was not fully investigated the splicing of which genes are regulated by USP15 and whether the regulated splicing affects cancer progression." (PMID 35027535, 2022). "Next, we examined whether the cancer progression ability of USP15 and USP4 is allied with SRSF1 alternative splicing." (PMID 35027535, 2022). "The relevance of USP15 in del(5q) MDS prompted us to examine the broader role of USP15 in cancers." (PMID 34465865, 2022). "USP15 has been reported to be involved in the regulation of various cancers and diseases, and the reported substrate functions of USP15 are conflicting, suggesting that USP15 may act as both an oncogene and a tumor suppressor in different contexts." (PMID 35203682, 2022). "Importantly, patients with low expression levels of USP15 showed increased expression of 17 different genes related to cancer progression and formation and decreased expression of 13 different genes known to suppress tumors." (PMID 35422093, 2022). "Therefore, we reviewed the diverse biological functions of USP15 in cancers and other diseases, suggesting the potential of USP15 as an attractive therapeutic target." (PMID 35203682, 2022). "As excessive IGF activity is reported to promote cancer progression, the induction or suppression of USP15-mediated IRS-2 deubiquitination by selective hormones may enable the fine-tuning of IGF-induced growth-promoting activity." (PMID 33946990, 2021). "Considering the relapse of BC due to tamoxifen resistance, we speculated USP15 may be increased the anti-cancer effect of tamoxifen in BC cells." (PMID 33771975, 2021). "The role of USP15 has been demonstrated in several cancer development." (PMID 33771975, 2021). "These molecular regulations by USP15 promote or suppress different types of RCD in cancer models." (PMID 33919439, 2021). "Consequently, the clinical application value of USP15 as a potential cancer target remains underestimated." (PMID 33946990, 2021). "In particular, USP15 draws specific attention because of the conflicting functions of its substrates in cancer biology, which raises the question of whether USP15 is more likely to act as a tumor suppressor or as an oncogene." (PMID 33946990, 2021). "Next, we investigated whether cancer-related biological pathway activation would be informative as a biomarker for USP15 dependency." (PMID 33378683, 2020).